AQP4 (aquaporin 4)
Diseases named in the same sentence as AQP4 in open-access papers (continued):
Sharing a sentence is not in itself a finding about the gene and the disease.
relapsing-remitting multiple sclerosis (14 papers, 2015 to 2025). The most common clinical variant of multiple sclerosis, characterized by recurrent acute exacerbations of neurologic dysfunction followed by partial or complete recovery. "The presence of AQP4-immunoglobulin G (AQP4-IgG) is a serological or laboratory hallmark of NMOSD that is used to distinguish NMOSD from relapsing-remitting multiple sclerosis (RRMS)." (PMID 32586353, 2020). "Although both NMOSD AQP4 + and relapsing-remitting multiple sclerosis (RRMS) are autoimmune inflammatory diseases, NMOSD AQP4 + is distinguished by a more severe clinical course, with higher symptom intensity and greater residual disability." (PMID 41057549, 2025). "We identified 28 consecutive newly diagnosed DMD-naïve relapsing-remitting MS patients and 12 consecutive AQP4 antibody-seropositive NMOSD patients." (PMID 36203996, 2022). "Sera from 48 patients with NMO/NMOSD and 48 patients with relapsing-remitting multiple sclerosis (RR-MS) were tested for anti-aquaporin-4 (AQP4) and anti-MOG antibodies with a cell-based assay." (PMID 25889963, 2015). "Emerging consensus supports distinction of treatment strategies from those typically used for relapsing remitting MS, and several groups debate whether to follow treatment protocols akin to those for AQP4-Ab NMOSD." (PMID 30671648, 2019). "Differently from relapsing-remitting multiple sclerosis (RRMS) a group of patients present aquaporin-4 (AQP4) antibodies in the serum." (PMID 41057549, 2025). "Twenty-eight relapsing-remitting multiple sclerosis (RRMS), 24 AQP4 + NMOSD, 28 MOGAD patients and 32 healthy controls (HCs) underwent clinical evaluation, MRI and optical coherence tomography (OCT) scan." (PMID 38646958, 2024). "Metabolomics data from patients with relapsing-remitting MS (RRMS) (n = 34) and antibody-positive NMOSD (Ab-NMOSD) (aquaporin-4 antibody n = 54, myelin oligodendrocyte glycoprotein antibody n = 20) were used to identify discriminatory plasma metabolites separating RRMS and Ab-NMOSD." (PMID 31659123, 2019). "In this study, 52 aquaporin-4 antibody serum-positive NMOSD patients, 18 relapsing-remitting multiple sclerosis (RRMS) patients and 17 healthy controls (HCs) were included for the next-generation sequencing (NGS)." (PMID 32547558, 2020). "Finally, in the neurologic [MS, NMOSD, OND] cohort, one relapsing-remitting MS (RRMS) patient, one NMOSD patient, and two HDs were positive for MOG autoantibodies; nine NMOSD patients were positive for AQP4 autoantibodies; and two HDs were positive for MuSK autoantibodies." (PMID 30824481, 2019).
malignant glioma (13 papers, 2015 to 2025). A grade III or grade IV glioma arising from the central nervous system. "Targeting AQP4 has been explored as a potential strategy for reducing tumor-associated swelling and spread in malignant gliomas." (PMID 40575267, 2025). "In addition, a correlation between increased BBB permeability and elevated AQP4 levels has been observed, and AQP4 up-regulation is also associated with brain edema formation in malignant gliomas." (PMID 28423683, 2017). "Increased expression of AQP4 leads to a reduced OS in malignant gliomas, resulting in a poor prognosis." (PMID 38383423, 2024). "They found that in GBM samples, cell status varies depending on the amount of AQP4 expression, demonstrating significant heterogeneity within malignant gliomas with various AQP4 expression ratios." (PMID 39247976, 2024). "Research suggested that the dynamics of the aggregation of Aquaporin-4 (AQP4) into AQP4-OAP isoforms can trigger cell shape changes in malignant glioma cells." (PMID 39200356, 2024). "Here, we investigated the relationship between AQP4 and some K+ channels in the malignant glioma U87 line." (PMID 39200356, 2024). "We performed single-cell RNA transcriptome sequencing of 53059 cells from 13 malignant glioma samples and spotted that the expression of AQP4 differed between samples." (PMID 36599974, 2023). "We found that increased expression of AQP4 can lead to reduced OS in malignant gliomas, resulting in a poor prognosis." (PMID 36599974, 2023). "We performed AQP4-related analyses of different types of cells in malignant glioma samples using single-cell transcriptome analysis." (PMID 36599974, 2023). "Briefly, our study revealed substantial heterogeneity within malignant gliomas with different AQP4 expression levels, indicating the intricate connection between tumor cells and the tumor immune environment." (PMID 36599974, 2023). "The most recent research indicates that temozolomide can suppress the growth of malignant glioma by inhibiting the expression of AQP4, implying that the AQP4 pathway’s activity substantially impacts the chemotherapeutic effectiveness of GBM." (PMID 36523816, 2022). "In contrast, temozolomide (an effective drug for malignant glioma) decreases AQP4 expression level with increasing p38 MAPK phosphorylation, which is blocked by p38 MAPK inhibitor." (PMID 31178701, 2019). "More research should be conducted to elucidate the potential roles of AQP4 in malignant glioma for identifying the tumor type, progression stages and optimal treatment strategies." (PMID 28423683, 2017). "To date, several studies have demonstrated AQP4-mediated migration, but the mechanisms of the extent of AQP4 involvement in malignant glioma still requires more research." (PMID 28423683, 2017). "More effort should be directed toward clarifying the newly discovered functions and molecular mechanisms of AQP4 in malignant gliomas." (PMID 28423683, 2017). "The authors identified that TMZ might have therapeutic potential for controlling proliferation, invasion of malignant glioma by inhibiting AQP4 expression through activation of p38 signal transduction pathway." (PMID 39247976, 2024). "Intriguingly, temozolomide (TMZ), a standard first-line drug for malignant glioma, has also been found to have therapeutic potential for controlling proliferation, invasion of malignant glioma by inhibiting AQP4 expression through activation of p38 signal transduction pathway." (PMID 39247976, 2024). "Recently conducted research has demonstrated that temozolomide can hinder malignant glioma progression by suppressing AQP4 expressions, and suggests this could potentially lead to the discovery of novel therapeutic strategies for GBM." (PMID 39247976, 2024). "The role of AQP4 protein aggregation into OAP in malignant gliomas is still unclear." (PMID 36523816, 2022). "Here, we review the expression pattern and predictive significance of AQP4 in malignant glioma." (PMID 28423683, 2017).
malignant glioma (continued). "Intriguingly, there are some discrepancies regarding the role of AQP4 in malignant gliomas." (PMID 28423683, 2017). "Further discovery of the dynamics of OAPs and AQP4 molecules in tumor may be critical to gain insight into the potential role of AQP4 in malignant glioma regarding the prevention, treatment, and classification of the tumor type and progression stages." (PMID 28423683, 2017). "Of these, AQP1 and AQP4 proteins are found highly expressed in the most malignant gliomas." (PMID 26083629, 2015). "Molecules of this kind might be also useful in reducing AQP4 activity in malignant gliomas." (PMID 27367682, 2016). "In both LGG and high-grade gliomas (HGG), AQP4 expression remained significantly higher in tumor tissues compared to normal tissues, and AQP4 mRNA levels correlated strongly with its protein expression." (PMID 40788933, 2025). "By performing differential expression analysis on our malignant glioma samples, we identified four DEGs, CD74, HES1, CALD1, and HEBP2, significantly upregulated in the AQP4 high expression group." (PMID 36599974, 2023). "At present, some studies suggest AQP4 may be a marker for the progression of malignant glioma, while others argue that AQP4 has no impact on the overall survival of IDH-wildtype GBMs." (PMID 36599974, 2023).
infarction (12 papers, 2015 to 2025). A localised pathological necrosis of tissue resulting from obstruction of the blood supply usually by a thrombus, an embolus, or vascular torsion. "At the neural microenvironment, removal of astrocytic processes disables their ability to buffer extracellular K+ and glutamate through AQP4 in the infarction area, thereby causing excitotoxicity of neurons in the ischemic regions." (PMID 32985231, 2020). "The mRNA expression of Gsk3b and Aqp4, as the direct target gene for miR-29a-5p, was decreased in the peri-infarction tissue after intervention with miR-29a-5p agomir." (PMID 40529227, 2025). "In the cortex, pERK1/2 and aquaporin 4 expressions increased significantly in the infarction area, while glial fibrillary acidic protein (GFAP) reduced significantly compared with the noninfarction side in brain cortex." (PMID 32985231, 2020). "Therefore, for assessing AQP4 polarization, we placed ROIs in the transition area adjacent to the cortical and striatal infarction." (PMID 40837880, 2025). "This difference suggests that the extract may regulate brain water balance more effectively during the acute phase of infarction, likely by reducing the pathological overexpression of AQP4 and thereby limiting edema-related structural disruption." (PMID 41465215, 2025). "Notably, T3 can attenuate infarction and related edema by suppressing expression of aquaporin-4 water channels." (PMID 31454331, 2019). "Compared with I/R group, both the independent and combined use of GRb1 and Emodin could alleviate NDS, reduce the BBB permeability, reduce the infarction area and down-regulate Cx43 and AQP4 expression at 6h, 1d, 3d, and 7d after I/R (P < 0.05)." (PMID 30233364, 2018). "In conclusion, the combined use of Emodin and GRb1 could additively alleviate NDS, reduce the BBB permeability, reduce the infarction area and down-regulate Cx43 and AQP4 expression after I/R." (PMID 30233364, 2018). "Furthermore, edaravone markedly reduced AQP4 immunoreactivity and protein levels in the cerebral infarct area." (PMID 25904843, 2015). "Interestingly, AQP4 is a target of miR-29b and the overexpression of miR-29b significantly mitigates AQP4 expression with concomitant reduction of BBB disruption, edema, and infarction volume in a mouse model of focal ischemia." (PMID 32937836, 2020).
meningioma (12 papers, 2018 to 2026). A generally slow growing tumor attached to the dura mater. "Overexpression of AQP4 has been observed in meningiomas, which is associated with the response to vasogenic edema of meningiomas." (PMID 39944892, 2025). "We investigated AQP4/TRPV4 channel co-expression in meningiomas along with the neovascularization of tumors and associate with PTBE." (PMID 33538957, 2021). "For example, in meningioma it was associated with aquaporin 4 expression, a water channel protein in cell membranes." (PMID 29719621, 2018). "Quantification of AQP4 expression, using the labeling index (LI), revealed statistically lower levels of AQP4 in high-grade meningiomas (WHO, grades II and III) compared with WHO, grade I meningiomas." (PMID 33538957, 2021). "In 35% of meningiomas, AQP4/TRPV4 co-expression in ≥ 10% tumor cells (LI ≥ 10) was observed over a wide range in the tumor body but its expression in tumoral tissues nearby or to invading the meninges increased significantly." (PMID 33538957, 2021). "In the present study, expression of AQP4 was analyzed in meningioma samples taken from 174 patients, and in leptomeninges found in normal brain specimens and in some tumors." (PMID 33538957, 2021). "AQP4 and TRPV4 expression is rather associated with a response to vasogenic edema of meningiomas than with edema formation." (PMID 33538957, 2021). "Apart from VEGF-A pathway activation, the existence of peritumoral edema (PTBE) in meningiomas has been correlated with the expression levels of water transporter aquaporin 4 (AQP4)." (PMID 33538957, 2021). "The aim of this study was to investigate the co-expression of AQP4/TRPV4 in meningothelial cells and associate it with PTBE in meningiomas." (PMID 33538957, 2021). "Our data suggest that the microvascular density, contrary to AQP4 and/or TRPV4 expression, is strongly associated with PTBE extent in meningiomas." (PMID 33538957, 2021). "Meningioma cells demonstrated moderate to strong cytoplasmic immunoreactivity for AQP4 and TRPV4 channel expression." (PMID 33538957, 2021). "Only in one other study AQP4 expression has been evaluated in different grades of meningiomas and was found that the cytoplasmic AQP4 expression is not dependent on tumor grade." (PMID 33538957, 2021). "Previous studies in meningiomas, the neoplastic counterpart of meningothelial cells, proposed AQP4 as a possible factor in PTBE formation in terms of abnormal water transport over cell membranes." (PMID 33538957, 2021). "Peritumoral edema in meningiomas was dependent on the expression of AQP-4." (PMID 35692419, 2022). "Cytoplasmic AQP4 expression was detected in meningothelial cells of leptomeninges and meningiomas." (PMID 33538957, 2021). "Indeed, AQP4 was significantly overexpressed in peri-meningioma tissue compared with the main tumor of edematous meningiomas." (PMID 33538957, 2021). "Other studies imply a role for AQP4 in edematous meningiomas independently of grade." (PMID 33538957, 2021). "AQP4 expression levels were significantly decreased in grade II and grade III meningiomas compared with grade I meningiomas (p = 0.02)." (PMID 33538957, 2021). "In the present study, we detected the co-expression of AQP4 and TRPV4 in 35% of meningiomas, specifically grade I. This finding drove us to investigate the relationship of this co-expression with edema formation and edema extent in these tumors." (PMID 33538957, 2021). "Fifty-eight percent of meningiomas were AQP4 immunonegative (LI < 10) and TRPV4 immunopositive (LI ≥ 10) or AQP4/TRPV4 immunonegative (LI < 10)." (PMID 33538957, 2021). "Functional experiments would clarify the exact action of a possible cooperation of AQP4 and TRPV4 in pathogenesis of meningiomas." (PMID 33538957, 2021). "A proportion of edematous (76.5%) and non-edematous (66.7%) meningiomas demonstrated co-expression in ≥ 10% of tumor cells (LI ≥ 10%) of AQP4 and TRPV4 channels." (PMID 33538957, 2021).
meningioma (continued). "Until now, the role of AQP4 in PTBE of meningiomas is not clear given that in vasogenic edema, water entry in the brain is AQP4-independent contrary to cytotoxic brain edema which is AQP4-dependent." (PMID 33538957, 2021). "This differential expression of AQP4 between the two groups of meningiomas reached no significance because of the small number of patients in the group with non-edematous meningiomas (n = 3)." (PMID 33538957, 2021). "These are contradicting data compared with a recent evidence for cooperation of TRPV4 with AQP4 in astrocytes which results in edema formation and may support the theory that PTBE in meningiomas depends on different mechanism from that of cytotoxic edema." (PMID 33538957, 2021). "Evaluation of AQP4/TRPV4 expression in peri-meningioma (peri-tumor) tissue compared with the main tumor of edematous meningiomas revealed significantly increased expression for AQP4 (p = 0.007) but not for TRPV4 (p > 0.05) in peri-meningioma tissue." (PMID 33538957, 2021). "Thus, as AQP4 may be in fact a feedback response to vasogenic edema, the co-upregulation and presumed synergistic role of AQP4 and TRPV4 in meningiomas with larger edema could also be a response to edema." (PMID 33538957, 2021). "Importantly, peri-meningioma tissue of edematous meningiomas demonstrated significantly increased expression for AQP4 (p = 0.007) but not for TRPV4 (p > 0.05) compared with the main tumor." (PMID 33538957, 2021). "However, increased expression of AQP4 in edematous vs non-edematous meningiomas as well as in meningiomas with larger edema (EI ≥ 2), was detected, confirming previous findings." (PMID 33538957, 2021). "Tissue obtained from meningioma patients demonstrated AQP4/TRPV4 co-expression in both edematous and non-edematous meningiomas, although in the surrounding peri-meningioma tissue, only AQP4 was upregulated." (PMID 34616399, 2021). "There was a significant correlation between AQP4 and TRPV4 expression levels in benign (WHO, grade I) (Spearman rho = 0.366, p < 0.0001) but not in high-grade (WHO, grades II and III) meningiomas (p ≥ 0.05)." (PMID 33538957, 2021). "AQP4 and TRPV4 were correlated in benign (WHO, grade I) (p < 0.0001) but not in high-grade (WHO, grades II and III) meningiomas (p > 0.05)." (PMID 33538957, 2021). "Peritumoral edema was unrelated to the expression of TRPV4 and much more neither the combination of AQP4 and TRPV4 since 76.5% of edematous and 66.7% of non-edematous meningiomas showed co-expression of AQP4 and TRPV4 channels." (PMID 33538957, 2021). "AQP4/TRPV4 co-expression was detected in both edematous and non-edematous meningiomas." (PMID 33538957, 2021).
meningitis (12 papers, 2007 to 2025). A disorder characterized by acute inflammation of the meninges of the brain and/or spinal cord. "Meningitis is rarely reported as the primary clinical manifestation of both anti-aquaporin-4 (AQP4)/ anti-myelin oligodendrocyte glycoprotein (MOG) antibody-negative NMOSD (NMOSDneg)." (PMID 33750325, 2021). "Using this route AQP4-IgG induces meningitis 120 h after the initial intraperitoneal injection of AQP4-IgG." (PMID 33679755, 2021). "CSF aquaporin-4 IgG correlated with active disease in NMOSD, while anti-cyclic citrullinated peptide antibodies were detected in RA-related meningitis." (PMID 41487889, 2025). "Our results align with those of Pavan and collaborators, as we did not observe increased AQP4 expression levels in the brains of the meningitis-affected rats compared to the brains of the sham control rats." (PMID 36036510, 2022). "In line with these recent findings, our Western blot analysis using brain homogenates clearly showed that upon experimental pneumococcal meningitis, AQP4 protein levels are not altered, comparing brain tissue of the rats from the sham and meningitis groups over time." (PMID 36036510, 2022). "In the Streptococcus pneumoniae meningitis model, deletion of AQP4 produced a significant reduction in ICP and brain water accumulation in mice, suggesting that improved clinical outcomes could be achieved via blockage of AQP4 function." (PMID 35890028, 2022).
rheumatoid arthritis (12 papers, 2012 to 2026). A chronic, systemic autoimmune disorder characterized by inflammation in the synovial membranes and articular surfaces. "The activation of IL-6 signal plays a major role in the pathogenesis of AQP4+ NMOSD as well as rheumatoid arthritis (RA)." (PMID 41596603, 2026).